USP7 (ubiquitin specific peptidase 7)
Diseases named in the same sentence as USP7 in open-access papers (continued):
Sharing a sentence is not in itself a finding about the gene and the disease.
HIV-1 infection (2 papers, 2018 to 2021). The type species of lentivirus and the etiologic agent of acquired immunodeficiency syndrome (AIDS). "Our studies suggest that USP7 may play an additional role in HIV-1 infection through its stabilization of DDX24." (PMID 30367141, 2018). "Silencing USP7 in H9 T cells, HLTF degradation was more efficient in shUSP7 cells in the presence of HIV-1 infection compared with its control cells (lanes 2 and 4)." (PMID 34630422, 2021).
Hyperglycemia (2 papers, 2023). An increased concentration of glucose in the blood. "In vivo, conditional knockout of Usp7 in the mouse embryonic pancreas causes a dramatic reduction in islet formation and hyperglycemia in adult mice, due to impaired NGN3-mediated endocrine specification during pancreatic development." (PMID 37117185, 2023). "In contrast, USP7 inhibits hyperglycemia by mitigating gluconeogenesis." (PMID 36834633, 2023).
inflammatory bowel disease (2 papers, 2024 to 2025). A spectrum of small and large bowel inflammatory diseases of unknown etiology. "USP7 is highly active in Treg cells, and depletion of USP7 in Treg cells in inflammatory bowel disease models deprives them of their ability to resolve inflammation, suggesting a role for USP7 in adaptive immunity." (PMID 39300775, 2024).
lentivirus infection (2 papers, 2022 to 2024). Virus diseases caused by the Lentivirus genus. "To investigate the biological function of USP7-mediated YY1 stabilization in CRC, we established stable cell lines with knockdown of YY1, USP7, or both using lentivirus infection." (PMID 38769122, 2024). "MDA-MB-231-DoxR-USP7-silencing and MDA-MB-231-PtxR-USP7-silencing cells were generated using a lentivirus infection system carrying USP7 shRNA, and used to further investigate the relationship between USP7 and chemoresistance in TNBC." (PMID 36291159, 2022).
lupus nephritis (2 papers, 2024). Glomerulonephritis in the context of systemic lupus erythematosus. "For example, USP4 has been shown to interact with and deubiquitinate RORγt, promoting its function and IL-17A transcription in rheumatic heart disease; similarly, USP7 has been found to promote lupus nephritis by regulating NF-κB p65 signaling via JMJD3 stabilization." (PMID 39134949, 2024). "Ubiquitin specific peptidase 7 (USP7) stabilizes JMJD3 via deubiquitylation, leading to increased pro-inflammatory gene expression related to the NF-κB pathway and lupus nephritis progression." (PMID 39315124, 2024).
metastatic melanoma (2 papers, 2021). A melanoma that has spread from its primary site to another anatomic site. "Additionally, ac-DNMT1 protein levels were also significantly positively correlated with TIP60 (r = 0.6, p < 0.0001) and USP7 (r = 0.74, p < 0.0001) protein levels in stage IV metastatic melanoma (n = 164)." (PMID 34572918, 2021). "There were significant positive correlations between USP7 and ac-DNMT1 protein levels in both stage III (r = 0.5, p = 0.04) and stage IV (r = 0.74, p < 0.0001) metastatic melanoma samples." (PMID 34572918, 2021). "We assessed 141 stage IV metastatic melanoma patients with age, gender, organ site, and ac-DNMT1/DNMT1/TIP60/USP7 H-scores in a regression model." (PMID 34572918, 2021). "Additionally, we observed a significant positive correlation between TIP60 and USP7 (r = 0.67, p = 0.003 for stage III; r = 0.8, p < 0.0001 for stage IV) protein levels in metastatic melanoma." (PMID 34572918, 2021).
myelodysplastic syndrome (2 papers, 2023 to 2024). A clonal hematopoietic disorder characterized by dysplasia and ineffective hematopoiesis in one or more of the hematopoietic cell lines. "Finally, further studies are needed to elucidate the role of USP7 in the pathogenesis of myelodysplastic syndrome." (PMID 37373211, 2023). "In summary, we demonstrated for the first time that the USP7, USP15, and UBE2T genes might be related to MDS pathogenesis and prognosis, supporting the importance of these genes in understanding the etiology and prognostic stratification of Myelodysplastic Syndrome." (PMID 37373211, 2023).
Myocardial fibrosis (2 papers, 2022 to 2024). "Due to the abnormal activation of USP7, SMAD3 was upregulated, which in turn increased the EndMT process of ECs, promoted myocardial fibrosis, and accelerated the progression of HFpEF." (PMID 39346543, 2024).
non-small cell lung adenocarcinoma (2 papers, 2020 to 2023). Type of epithelial lung cancer arising from glandular origin.
ovarian tumor (2 papers, 2012 to 2016). "Next, we tested the FP reagents in deconjugation assays by treating them with three human deubiquitylating enzymes (DUBs; UCH-L3, USP7/HAUSP and USP21), two viral ovarian tumour domain (OTU) DUBs and three SUMO-specific proteases (SENP1, SENP6 and SENP7)." (PMID 22213387, 2012).
prostate tumor (2 papers, 2017 to 2019). "Appreciable levels of CCDC6 and USP7 proteins have been observed in a series of prostate tumor cell lines independently of the expression of androgen receptor." (PMID 28415632, 2017). "Thus, our data suggest that the USP7 inhibition represents a compelling therapeutic strategy for hormone-sensitive and androgen-resistant prostate tumors." (PMID 28415632, 2017). "Moreover, the inhibition of USP7 enzyme could be considered an ideal treatment, in combination with the PARP inhibitors, in both hormone-sensitive and androgen-resistant prostate tumors that express USP7 and CCDC6." (PMID 28415632, 2017). "Thus, besides the effects of USP7 inhibitors on the stability of AR isoforms and their transcriptional gene targets, we asked whether the treatment with USP7 inhibitor was also able to affect the CCDC6 stability in prostate tumor cells." (PMID 28415632, 2017). "Interestingly, we have detected targettable levels of USP7 and CCDC6 in 68% of analysed tumors, in a Tissue Micro Array (TMA) of 28 primary prostate tumors." (PMID 28415632, 2017). "Thus, CCDC6 and USP7 might represent novel predictive biomarkers for the combined treatment of the USP7 inhibitors and PARP inhibitors in both hormone-sensitive and androgen-resistant prostate tumors." (PMID 31242618, 2019).
acute respiratory distress syndrome (1 paper, 2025). Progressive and life-threatening pulmonary distress in the absence of an underlying pulmonary condition, usually following major trauma or surgery. "USP7‐mediated ICAM1 induced apoptosis, inflammation, oxidative stress, and M1 macrophage polarization, while suppressed proliferation in LPS‐induced HPMECs via activating NF‐κB pathway, thus accelerating the progression of pediatric acute respiratory distress syndrome." (PMID 40329406, 2025).
allergic disease (1 paper, 2025). An immune response that occurs following re-exposure to an innocuous antigen, and that requires the presence of existing antibodies against that antigen. "The USP7-STAT3-Granzyme-PAR-1 axis significantly influenced Th2 cell differentiation by regulating the production and activity of GzmA and GzmB, as well as the phosphorylation of STAT3 by USP7, particularly in the production of IL-5 and IL-13, which played a key role in allergic diseases." (PMID 40893770, 2025).
amyotrophic lateral sclerosis (1 paper, 2022). Amyotrophic lateral sclerosis (ALS) is a neurodegenerative disease characterized by progressive muscular paralysis reflecting degeneration of motor neurons in the primary motor cortex, corticospinal tracts, brainstem and spinal cord. "Emerging evidence suggests that USP7 controls the stability of a diverse set of substrates and is involved in a range of cellular processes, including tumorigenesis, adipocyte differentiation, amyotrophic lateral sclerosis (ALS) pathogenesis, inflammasome activation, and antiviral signaling." (PMID 36032091, 2022).
arthropathy (1 paper, 2024). Any disorder of the joints. "Our results were consistent in that there is a causal relationship between the gene expression and methylation of ARNTL, USP7, KRAS and UC with arthropathy, and can be the potential target of UC with arthropathy." (PMID 38302916, 2024).
cervical adenocarcinoma (1 paper, 2015). An adenocarcinoma arising from the cervical epithelium. "Our results suggest that increased levels of MLL5 protein are correlated with upregulation of OGT and USP7 in primary cervical adenocarcinomas." (PMID 26678539, 2015). "MLL5 protein levels were additionally correlated with increased OGT and USP7 expression in primary cervical adenocarcinomas." (PMID 26678539, 2015). "Levels of MLL5, OGT and USP7 in 8 pairs of human cervical squamous cell carcinoma and 2 pairs of human cervical adenocarcinoma and adjacent normal tissues were analyzed via immunostaining with the appropriate antibodies." (PMID 26678539, 2015). "In addition, upregulation of MLL5 expression was correlated with increased expression of OGT and USP7 in human primary cervical adenocarcinomas." (PMID 26678539, 2015). "Notably, upregulation of MLL5 is correlated with increased expression of OGT and USP7 in human primary cervical adenocarcinomas." (PMID 26678539, 2015). "Here, we detected increased protein expression of OGT, USP7 and MLL5 in human primay cervical adenocarcinomas, compared with adjacent normal tissues." (PMID 26678539, 2015).
cholangiocarcinoma (1 paper, 2025). A carcinoma that arises from the intrahepatic biliary tree (intrahepatic cholangiocarcinoma) or from the junction, or adjacent to the junction, of the right and left hepatic ducts (hilar cholangiocarcinoma). "Under hypoxic conditions, SKA3 recruits PARP1 to bind with HIF-1α, thereby enhancing USP7-mediated deubiquitination of HIF-1α, promoting the proliferation and fatty acid synthesis of cholangiocarcinoma cells." (PMID 39944823, 2025).
chronic kidney disease (1 paper, 2022). Impairment of the renal function secondary to chronic kidney damage persisting for three or more months. "Furthermore, in a cohort of patients with calculi-related chronic kidney disease, upregulated FAT10 expression was positively correlated with renal fibrosis and the USP7/CHK1 axis." (PMID 36152057, 2022). "These novel findings indicate that FAT10 prolongs CHK1-mediated G2/M arrest via USP7 to promote renal fibrosis, and inhibition of the FAT10/USP7/CHK1 axis might be a plausible therapeutic approach to alleviate renal fibrosis in chronic kidney disease." (PMID 36152057, 2022).
cocaine addiction (1 paper, 2023). "Furthermore, we uncover genetic variations in MAGED1 and USP7 associated with altered susceptibility to cocaine addiction and to cocaine-induced aggressive behavior in human subjects." (PMID 38123574, 2023). "Additionally, genetic variations in MAGED1 and USP7 are linked to altered susceptibility to cocaine addiction and cocaine-associated symptoms in humans." (PMID 38123574, 2023). "Indeed, SNP mutations in USP7 and MAGED1 among polydrug users were associated with varying scores of aggressiveness during cocaine use and a modified transition time to cocaine addiction, respectively." (PMID 38123574, 2023). "To assess the potential contributions of MAGED1 and USP7 to CUD directly in humans, we conducted a within-case MAGED1 and USP7 gene analysis with 351 consecutively recruited outpatients with cocaine addiction and genetically verified Caucasian ancestry." (PMID 38123574, 2023).
colonic adenocarcinoma (1 paper, 2023). "In addition, co-localization of USP7 and SAMHD1 was identified in colonic adenocarcinoma tissues while this phenomenon was only rarely observed in peritumoral tissues." (PMID 37081042, 2023).
COVID-19 (1 paper, 2023). A disease caused by infection with severe acute respiratory syndrome coronavirus 2. "Furthermore, USP7 is known to be involved in the replication of the SARS-CoV-2 virus, which is highly relevant to the context of COVID-19." (PMID 37888725, 2023).
dengue (1 paper, 2019). "Upon dengue NS5 overexpression, another important DUB the USP7 expression level was also checked." (PMID 32123831, 2019).
disc degeneration (1 paper, 2025). "Together, these findings uncover a novel immune-inflammatory mechanism underlying IDD and highlight the USP7-mediated pathway in monocytes as a potential therapeutic target for modulating disc degeneration." (PMID 40947005, 2025).
embryonal carcinoma (1 paper, 2021). A non-seminomatous malignant germ cell tumor characterized by the presence of large germ cells with abundant cytoplasm resembling epithelial cells, geographic necrosis, high mitotic activity, and pseudoglandular and pseudopapillary structures formation. "Appreciable levels of CCDC6 and USP7 proteins were detected in NTERA-2 human Embryonal Carcinoma and in the murine GC-1 spermatogonia cells, while nearly undetectable amount was observed in GC-2 spermatocytes and TM4 Sertoli cells." (PMID 34841108, 2021).
endometriosis (1 paper, 2015). The growth of functional endometrial tissue in anatomic sites outside the uterine body. "The USP7 gene has a G→A substitution in intron 25 (rs1529916: g.8897333G>A), and derived allele A has been associated with endometriosis, female infertility, and prostate cancer." (PMID 26382048, 2015).
Fanconi anemia (1 paper, 2023). Fanconi anemia (FA) is a hereditary DNA repair disorder characterized by progressive pancytopenia with bone marrow failure, variable congenital malformations and predisposition to develop hematological or solid tumors. "USP1 targets FANCD2/FANCI to regulate the Fanconi anemia pathway (FA) and, together with USP7, targets translesional DNA repair (TLS)." (PMID 37892185, 2023). "The DUB proteins USP1, OTUB1, UCHL5, USP7, and PSMD14 were reported to contribute to double-strand break repair, USP1 to Fanconi anemia pathway, USP1 and USP7 to translesion repair, USP7 and USP47 to base excision repair, and USP7 and USP45 to nucleotide excision repair." (PMID 37892185, 2023).
hepatic disorders (1 paper, 2023). "The roles of USP7 and 22 in hepatic disorders are controversial." (PMID 36834633, 2023).
Herpes simplex infection (1 paper, 2019). "The CLOCK and USP7 genes were included in the Herpes simplex infection pathway." (PMID 31214170, 2019).
herpesvirus infection (1 paper, 2024). "Interestingly, multiple KSHV proteins also interact with USP7, strengthening the critical role of USP7 in herpesvirus infection." (PMID 38215174, 2024).
intestinal tumor (1 paper, 2023). "Loss of Usp7 prolongs the survival of the sporadic intestinal tumor model and is well tolerated in healthy intestine." (PMID 36669491, 2023). "Quantitative RT-PCR analysis of the isolated tumors showed that expression of the WNT target genes and stem cell markers Lgr5, Ascl2, and Axin2 were suppressed in the Usp7 cKO tumors, suggesting that Usp7 depletion inhibits WNT signaling in the Apc-deficient intestinal tumors." (PMID 36669491, 2023). "Loss of Usp7 prolongs the survival of the sporadic intestinal tumor model." (PMID 36669491, 2023). "Altogether, these results indicate that inhibition of Usp7 suppresses intestinal tumor development and progression mediated by Apc-truncating mutations." (PMID 36669491, 2023). "Here, we show in vivo that deletion of Usp7 in Apc-truncated mice inhibits crypt hyperproliferation and intestinal tumor development." (PMID 36669491, 2023). "We further investigated the role of Usp7 in CRC using two independent mouse intestinal tumor models (Apcmin and Apchet) that mimic human patients with FAP with germline APC mutations predisposed to CRC development." (PMID 36669491, 2023). "In this article, Li and colleague show that deletion of Usp7 in Apc-truncated mice inhibits crypt hyperproliferation and intestinal tumor development." (PMID 36669491, 2023). "Since Usp7 depletion induces gut inflammation in animals with germline Apc mutation only but not in normal WT mice, we asked if Usp7 inhibition can improve the survival of sporadic intestinal tumor." (PMID 36669491, 2023).
ischemia (1 paper, 2024). A hypoperfusion of the BLOOD through an organ or tissue caused by a PATHOLOGIC CONSTRICTION or obstruction of its BLOOD VESSELS, or an absence of BLOOD CIRCULATION.
Lewis lung carcinoma (1 paper, 2020). "USP7 inhibitors delayed tumor growth in mice with Lewis lung carcinoma, and promoted tumor infiltration of M1 MΦs and IFN-γ+CD8+T cells." (PMID 32802195, 2020).
liver cirrhosis (1 paper, 2020). "High USP7 level was associated with tumor size (P = 0.018), tumor differentiation (P = 0.007), advanced TNM stage (P = 0.004) and liver cirrhosis (P = 0.025)." (PMID 32002017, 2020).
methamphetamine dependence (1 paper, 2025). A drug dependence that is a psychological dependency on the regular use of methamphetamine. "Notably, the observed hypomethylation of GABRB1, and KCNQ2, along with the hypermethylation of CES1 and USP7, may underlie the pathophysiology of methamphetamine dependence." (PMID 41368944, 2025). "Methylation levels in CG sites in CES1 showed high diagnostic accuracy (AUC = 0.755) for methamphetamine dependence, while the AUC values for KCNQ2 and USP7 were 0.68 and 0.664, respectively, indicating moderate classification." (PMID 41368944, 2025).
neuroendocrine tumor (1 paper, 2017). "Moreover, we have observed a lethal effect combining the inhibitors of USP7 and PARP enzymes in lung neuroendocrine tumor expressing USP7 and CCDC6 proteins." (PMID 28415632, 2017).
Osteopenia (1 paper, 2023). Osteopenia is a term to define bone density that is not normal but also not as low as osteoporosis. "Further exploring the pathophysiological role of USP7 in bone, we uncovered that USP7 is abnormally decreased in osteopenia mice." (PMID 37199589, 2023). "Additionally, the decreased expression of USP7 in osteopenia mice suggests a critical role in abnormal bone homeostasis and disease." (PMID 37199589, 2023).
pituitary tumor (1 paper, 2021). A benign or malignant neoplasm affecting the pituitary gland. "Collectively, these data suggested that NEK2 is a specific substrate of USP7 in pituitary tumor cells." (PMID 33754007, 2021). "We posit that targeting USP7 or NEK2 might have therapeutic potential in pituitary tumors, especially dopamine-resistant tumors marked by high NEK2 expression." (PMID 33754007, 2021).
pneumonia (1 paper, 2025). An acute, acute and chronic, or chronic inflammation focally or diffusely affecting the lung parenchyma, caused by an infection in one or both of the lungs (by bacteria, viruses, fungi, or mycoplasma.). "In particular, it has been reported that USP7-dependent mitogen-activated protein kinase 14 (MAPK14) aggravates the progression of pneumonia." (PMID 40121492, 2025). "As previously documented, USP7 interacted with MAPK14, thereby playing a role in the regulatory mechanisms of esculin in the context of LPS-induced pneumonia." (PMID 40121492, 2025).
postmenopausal osteoporosis (1 paper, 2023). Metabolic disorder associated with fractures of the femoral neck, vertebrae, and distal forearm. "To evaluate the potential role of USP7 in bone metabolism in vivo, we performed ovariectomy in mice, as an animal model of postmenopausal osteoporosis." (PMID 37199589, 2023).